MYC (MYC proto-oncogene, bHLH transcription factor)
Diseases named in the same sentence as MYC in open-access papers (continued):
Sharing a sentence is not in itself a finding about the gene and the disease.
B-cell lymphoma (continued). "Diffuse B-cell lymphomas with concurrent MYC and BCL2 rearrangements are aggressive neoplasms, although there is some pathologic heterogeneity." (PMID 38978094, 2024). "Further, XPO1 inhibition decreased cell fitness in other MYC-driven tumors including human P493-6 Burkitt lymphoma-like, a murine MYC-induced T-cell leukemia and a murine IgH-MYC B-cell lymphoma cell line." (PMID 38302473, 2024). "High-grade B-cell lymphoma with MYC and BCL2 rearrangements was detected in 9% of all large B-cell lymphoma specimens, including one case with rearrangements at all three loci MYC, BCL2, and BCL6; MYC and BCL6 rearrangements were found in 1.6% of specimens." (PMID 38903717, 2024). "A retrospective analysis of all diffuse large B-cell lymphomas and high-grade B-cell lymphomas with MYC and BCL2 and/or BCL6 rearrangements diagnosed between 2017 and 2021 at the Institute of Oncology Ljubljana, Slovenia, has been performed." (PMID 38397877, 2024). "High-grade B-cell lymphoma with MYC and BCL2 rearrangements comprised 9% of all large B-cell lymphoma specimens in our cohort, typical of the 8–10% rate reported in the literature." (PMID 38903717, 2024). "Experimental evidence for this translocation being a driver of B cell lymphomas was provided by one of the first mouse transgenic cancer models, in which the c-MYC gene was coupled to IgH μ enhancer sequences to establish the Eμ-Myc mouse line." (PMID 38616733, 2024). "Fluorescence in situ hybridization (FISH) is an essential ancillary study used to identify clinically aggressive subsets of large B-cell lymphomas that have MYC, BCL2, or BCL6 rearrangements." (PMID 38903717, 2024). "One study suggests higher rates of BMB/PET discrepancies among elderly patients and those with high-grade B-cell lymphoma with MYC and BCL2 and/or BCL6 rearrangements." (PMID 38535078, 2024). "CHK1/WEE1 inhibitors also show promise in B-cell lymphomas and would be of particular interest in MYC driven subsets given their high replication stress." (PMID 38347838, 2024). "In contrast, Ig/MYC rearrangements induce MYC overexpression in B cell lymphomas, such as Burkitt’s lymphoma and plasmablastic lymphomas." (PMID 38318177, 2024). "A total of 222 specimens from 208 unique patients were identified with a large/high-grade B-cell lymphoma diagnosis and performance of either MYC, BCL2, or BCL6 FISH." (PMID 38903717, 2024). "Peripheral blood FISH (fluorescence in-situ hybridization) analysis showed evidence of high-grade B-cell lymphoma (HGBCL) with MYC (36.5%) and BCL2 (92.9%) rearrangements." (PMID 39449881, 2024). "High-grade B-cell lymphoma with MYC and BCL6 rearrangements was much less common in our cohort with 3 cases out of 182 specimens rearranged at both loci (1.6%)." (PMID 38903717, 2024). "B-cell lymphomas with concurrent MYC, BCL2, BCL6, and CCND1 rearrangements appear to be a rare occurrence; however, current standard approaches to DLBCL/HGBL classification do not require routine testing for CCND1 rearrangement." (PMID 38914869, 2024). "Recent updates have removed certain categories, including the previously unclassifiable “B-cell lymphoma” that was identified by “high-grade B-cell lymphoma, with MYC and BCL-2 and/or BCL-6 rearrangements”." (PMID 38535155, 2024). "MYC, a master transcriptional regulator of cancer cell growth (mass) and metabolism, is overexpressed by chromosomal translocations or other means in B-cell lymphomas." (PMID 39125743, 2024). "Zanubrutinib is a BTK inhibitor reported to be effective for B‐cell lymphomas with MYD88 and CD79b mutations, double expression of MYC and BCL2/BCL6, and CD5 expression." (PMID 39054569, 2024).
B-cell lymphoma (continued). "FISH demonstrated MYC, BCL2, BCL6, and CCND1 rearrangements and the diagnosis of high-grade B-cell lymphoma with MYC, BCL2, BCL6, and CCND1 was rendered." (PMID 38914869, 2024). "Altogether, these analyses led us to conclude that, as in Eμ-Myc mice, ACKR4 is a male-specific positive prognostic factor in Burkitt lymphoma, the archetype of MYC-driven B-cell lymphomas." (PMID 39298333, 2024). "We previously reported that USP29 stabilizes oncogenic MYC (including c-MYC and N-MYC) and HIF1α in normoxia and hypoxia, respectively, thereby promoting tumor metabolism and progression in c-MYC driven B cell lymphoma and N-MYC driven neuroblastoma." (PMID 38233848, 2024). "B-cell lymphomas with MYC and BCL6 rearrangements are now reclassified as a subtype of DLBCL, NOS or HGBL, NOS according to their cytomorphological features." (PMID 38914869, 2024). "We have shown that MYC coordinately induces the transcription of enzymes that direct the polyamine–hypusine circuit and, accordingly, levels of eIF5AHyp are significantly elevated in both human and mouse B-cell lymphoma with MYC involvement." (PMID 39125743, 2024). "Previous studies showed that IBTK is a potential transcriptional target of MYC in aggressive MYC-driven B cell lymphomas." (PMID 38371626, 2024). "It was felt to be best considered, as the submitters did, a high-grade B-cell lymphoma with MYC and BCL6 rearrangement with CD5 and SOX11 expression." (PMID 37530792, 2024). "Baseline characteristics were well balanced, with slightly more cases of high-grade B-cell lymphoma with MYC and BCL2 or BCL6 rearrangement in the tisa-cel arm (20% vs. 12%)." (PMID 38893108, 2024). "Three specimens of 182 (1.6%) showed MYC and BCL6 rearrangements, which according to the ICC, is diagnostic of the provisional entity high-grade B-cell lymphoma with MYC and BCL6 rearrangements." (PMID 38903717, 2024). "Tumor cells from B-cell lymphoma/leukemia patients and λ-MYC mice, a B-cell lymphoma mouse model, overproduce glutathione." (PMID 39068166, 2024). "Specifically, miR-125a has been reported to reduce malignancy in MM cells by targeting the angiogenesis factors and deubiquitinase USP5, while miR-28-5p controls cell proliferation and MYC activation in B-cell lymphomas." (PMID 37048103, 2023). "Aggressive B‐cell lymphomas with MYC and BCL2 rearrangements form a molecularly distinct group and are listed as definite entities in both classifications." (PMID 36918411, 2023). "Selective inhibition of cytoplasmic HDAC6 by the HDAC6 inhibitor 34 (marbostat) led to MYC degradation and apoptosis in MYC-overexpressing B-cell lymphoma cells." (PMID 36835501, 2023). "Among hematopoietic malignancies, genomic abnormalities involving the MYC gene are almost always found in B-cell lymphomas but rarely in T cell lymphomas." (PMID 36966168, 2023). "This is in contrast to the more heterogeneous group of aggressive B‐cell lymphomas with MYC and BCL6 rearrangements that are recognized as a provisional entity in the ICC, while they fall into the DLBCL, NOS, or the HGBL, NOS, groups in the WHO-HAEM5." (PMID 36918411, 2023). "SRA737 demonstrated favorable safety and efficacy when combined with gemcitabine in preclinical non-small cell lung cancer (NSCLC) and MYC-driven B-cell lymphoma mouse models." (PMID 37987002, 2023). "Cases harbouring both MYC and BCL2 rearrangements are better classified as high-grade B cell lymphoma (HGBCL) with MYC and BCL2 rearrangement." (PMID 36278991, 2023). "In fact, MYC overexpressing lymphomas such as high-grade B-cell lymphoma (HGBL) and double expressor diffuse large B-cell lymphomas (DLBCL), are considered addicted to MYC." (PMID 37457123, 2023).
B-cell lymphoma (continued). "Major oncogenes frequently associated with particular types of B-cell lymphoma are BCL2 (FL, DLBCL), BCL6 (DLBCL), CCND1 (MCL, MM), and MYC (BL, DLBCL)." (PMID 37371852, 2023). "Studies have shown that AID plays a crucial role in the development of mature B-cell lymphomas in Eμ-c-MYC transgenic mice." (PMID 37600817, 2023). "WHO-HAEM4R had introduced two categories of HGBL, namely “high-grade B-cell lymphoma with MYC and BCL2 and/or BCL6 rearrangements” and “high-grade B-cell lymphoma, not otherwise specified (NOS)”." (PMID 37190213, 2023). "Cell line models of hepatocellular carcinoma and B-cell lymphoma driven by MYC overexpression showed sensitivity to CDK9 inhibitors." (PMID 36966168, 2023). "A number of other LBCLs are infrequently or rarely show EBV infection such as HHV8+ DLBCL, high grade B-cell lymphoma/DLBCL with MYC and BCL2/BCL6 rearrangements and primary mediastinal LBCL." (PMID 36836878, 2023). "In the initial description of the model, λ-MYC mice were reported to develop mature B cell lymphomas that share several features with human BL, with a lifespan ranging from 38 to 216 days." (PMID 37809061, 2023). "MYC oncogene aberrations, including translocations or overexpression, are characteristics of B-cell lymphoma aetiology." (PMID 36900005, 2023). "In MYC-deregulated B-cell lymphomas, inhibition of ALKBH5 also suppresses the growth of tumor cells by enhancing expression of MYC-repressed genes like SPI1 and PHF12146." (PMID 37928272, 2023). "The extensively studied oncogene MYC, able to control essential cellular processes such as proliferation, is dysregulated in a variety of B-cell lymphomas." (PMID 37600821, 2023). "DLBCL/high-grade B-cell lymphoma with MYC and BCL2 and/or BCL6 rearrangements carries a particularly poor prognosis." (PMID 36836878, 2023). "A recent study, investigating the use of DL for the inference of MYC rearrangements from biopsies of patients with aggressive B-cell lymphoma, confirmed the potential value of this technology, demonstrating a sensitivity of 0.93." (PMID 37958379, 2023). "Here, we summarize the different classes of molecules currently under development, which mostly target MYC indirectly in aggressive B-cell lymphomas, paying special attention to subtypes with MYC/BCL2 or BCL6 translocations or overexpression." (PMID 37457123, 2023). "The oncogenic HSP90, which optimizes several MYC metabolic programs, is indispensable to fulfill biomass, energetic, and secretory demands of B-cell lymphomas and, specifically, to support the metabolic process driven by MYC." (PMID 36982568, 2023). "Here we show that post-transcriptional mechanisms are responsible for the calcineurin (CN) independent constitutive nuclear over-expression of NFATc1 in BL and Eμ-MYC – induced B cell lymphomas (BCL)." (PMID 37546418, 2023). "High grade B-cell lymphoma with MYC and BCL2 rearrangements (HGBCL-DH) represents an uncommon B-cell lymphoma (BCL) with aggressive clinical courses and poor prognosis." (PMID 37899423, 2023). "First, DDX3X mutations occur with high frequency particularly in those GC-derived B-cell lymphomas that also show translocations of the c-MYC proto-oncogene, which occurs in almost all BL and a subset of DLBCL." (PMID 37035206, 2023). "In the present study, we also investigated the role of BCL-W in the development of MYC-driven B cell lymphoma." (PMID 37567974, 2023). "A key regulator in B cell lymphomas is the c-MYC transcription factor, whose deregulated expression is commonly associated with unfavorable prognosis." (PMID 37809061, 2023). "In these conditions, ascorbate synergized with IACS‐010759 to kill MYC‐overexpressing cells in vitro and reinforced its therapeutic action against human B‐cell lymphoma xenografts." (PMID 37158102, 2023).
B-cell lymphoma (continued). "HGBL includes two types: high-grade B-cell lymphoma, accompanied by MYC and Bcl-2 and/or Bcl-6 rearrangement (HGBLR), and high-grade B-cell lymphoma, not otherwise specified (HGBL, NOS), this type has a low incidence and is clinically rare." (PMID 36618391, 2022). "Next, we tested how the inhibition of MSI2 and PRMT5 affects c-MYC protein abundance in B-cell lymphoma cells." (PMID 36167829, 2022). "We give here an overview of GEMMs of MYC-induced B-cell lymphoma, revisiting over 170 GEMMs with distinct genetic alterations." (PMID 36611833, 2022). "MYC rearrangements are found frequently among non-Hodgkin B-cell lymphomas enforcing MYC overexpression." (PMID 36611833, 2022). "Using a genome-wide transposon mutagenesis screen in a MYC-driven B-cell lymphoma model, we here identify the SUMO isopeptidase (or deconjugase) SENP6 as a tumor suppressor that links unrestricted SUMOylation to tumor development and progression." (PMID 35022408, 2022). "Among 76 patients with high-grade B-cell lymphoma, 44 cases (57.9%) were high-grade B-cell lymphoma, accompanied by MYC and Bcl-2 and/or Bcl-6 rearrangement (HGBLR) patients, and 32 cases (42.1%) were HGBL, NOS patients." (PMID 36618391, 2022). "Within this framework, it is possible to argue that MYC-induced sumoylation promotes CSC survival in B-cell lymphoma." (PMID 35269436, 2022). "In our work, we reveal that M-100 treatment of B-cell lymphoma cells induces proteasomal degradation of MYC." (PMID 36068335, 2022). "As directly targeting MYC with chemical compounds is challenging, exploring genetic vulnerabilities in MYC-induced B-cell lymphoma is expected to uncover new “attack points” for cancer treatment." (PMID 36611833, 2022). "The percentage of high-grade B cell lymphoma with MYC rearrangement was, respectively, 6%, 17% and 13% in ZUMA-1, JULIET and TRANSCEND." (PMID 36009506, 2022). "Therefore, since overexpression of MYC is a feature of many types of cancer and results in DNA replication stress leading to genomic instability and tumorigenesis, we next investigated the effect of the RelA T505A mutation in the well-established Eμ-Myc mouse model of B-cell lymphoma." (PMID 36240065, 2022). "Not recognized by either NCI or DFCI are the actual high-grade B-cell lymphoma (HGBCL), B-cell lymphomas with MYC translocation together with either BCL2 and/or BCL6 translocation (double hit/triple hit)." (PMID 36387143, 2022). "In MYC-driven B-cell lymphoma, depletion of SENP6 leads to dissociation from chromatin of protein complex involved in DNA repair and genome maintenance, resulting in damage accumulation and genome instability." (PMID 35887358, 2022). "HGBL-DH/TH (high grade B-cell lymphoma with double/triple hits) harbor simultaneous translocations of MYC and BCL2 (DHL BCL2) or MYC and BCL6 (DHL BCL6), which associate with aggressive clinical course and inferior prognosis." (PMID 35884496, 2022). "Acting immediately downstream of ATR, targeting of Chk1 is effective in MYC-driven tumours including B-cell lymphomas owing to MYC-induced replication stress." (PMID 36505788, 2022). "In fact, oncogenic MYC increases the reliance upon mitochondrial metabolism in B‐cell lymphoma, as assessed in a cellular model of conditional MYC repression." (PMID 36214609, 2022). "Tubulin facilitates nuclear import of MYC, and MYC-dependent B-cell lymphoma cells rely on continuous import of MYC due to its high turn-over." (PMID 36068335, 2022). "The WHO-HAEM4R entity of high-grade B-cell lymphoma with dual rearrangements of MYC and BCL2 and/or BCL6 has been conceptually reframed and reassigned." (PMID 35732829, 2022). "In contrast, MYC phosphorylation at threonine residue 58 via GSK3 is destabilizing and frequently mutated in B-cell lymphoma to prevent phosphorylation and decay." (PMID 36611833, 2022).
B-cell lymphoma (continued). "Here, we show that inhibition of the histone deacetylase 6 (HDAC6) using the HDAC6 inhibitor Marbostat-100 (M-100) reduces oncogenic MYC levels and prevents lymphomagenesis in a mouse model of MYC-induced aggressive B-cell lymphoma." (PMID 36068335, 2022). "High-grade B-cell lymphoma with translocations involving MYC and BCL2 or BCL6, usually referred to as double hit lymphoma (DHL), is an aggressive hematological malignance with distinct genetic features and poor clinical prognosis." (PMID 35303910, 2022). "BL is defined as a high proliferation rate mature B-cell lymphoma with an isolated MYC translocation." (PMID 35897021, 2022). "In B-cell lymphoma, cAMP indirectly inhibits MYC expression and forms a positive feedback loop with MYC." (PMID 35978822, 2022). "Reciprocally, via positive feedback loops, MYC further upregulates cellular sumoylation in MYC-driven B-cell lymphomas by increasing the transcription of SUMO cascade enzymes." (PMID 35269436, 2022). "According to 2017 WHO classification, it was reclassified as high-grade B-cell lymphoma with rearrangement of MYC and BCL6." (PMID 35334633, 2022). "MYC rearrangements, copy number amplifications, or mutations are frequently found among non-Hodgkin B-cell lymphomas (B-NHL) and enforce MYC overexpression." (PMID 36611833, 2022). "A biopsy of the hepatic lesion confirmed an infiltration by a high-grade B cell lymphoma with MYC, BCL2 and BCL6 rearrangements." (PMID 36290900, 2022). "Taken together, our data demonstrate a beneficial role of HDAC6 inhibition in MYC-dependent B-cell lymphoma." (PMID 36068335, 2022). "In our study, the third case demonstrated a relapse within the eye after an initial systemic high-grade B-cell lymphoma with MYc and BCL6 rearrangements which was in complete remission as a result of allo and auto hematopoietic stem cell transplantations." (PMID 35334633, 2022). "Cases of B-cell lymphoma with a Burkitt-like appearance that lack MYC rearrangement, therefore, should be tested for the 11q gain/loss pattern." (PMID 35732829, 2022). "Some real-world cohorts also reported a higher proportion of high-grade B cell lymphoma with MYC rearrangements." (PMID 36009506, 2022). "MYC is a gene involved in cellular proliferation that has been found to be dysregulated in B-cell lymphomas." (PMID 35204484, 2022). "At the molecular level, NFAT2, but not NFAT1, is recruited to the c-MYC gene promoter leading to c-MYC over-expression, which is required for tumor maintenance together with the deregulation of other survival genes in aggressive B cell lymphomas." (PMID 34234374, 2021). "In patients with MYC-rearranged aggressive B-cell lymphomas, the currently available data suggests that DA-EPOCH-R has a relatively higher response rate and in some instances with improved survival." (PMID 33754004, 2021). "Double-hit and triple-hit B-cell lymphomas are high-grade B-cell lymphomas defined by the genetic rearrangements of c-MYC and BCL-2 and/or BCL-6, accordingly, by targeted fluorescence in situ hybridization (FISH) studies." (PMID 33692924, 2021). "High-grade B-cell lymphoma, with MYC and BCL2 and/or BCL6 rearrangements (double/triple-hit high grade B-cell lymphoma, HGBL-DH/TH) constitutes a provisional entity among B-cell malignancies with an aggressive behavior and dire prognosis." (PMID 33672644, 2021). "In 2016, the revised World Health Organization (WHO) guidelines classified this special type to a new category named high‐grade B‐cell lymphoma with rearrangements of MYC, BCL2 and BCL6." (PMID 34698437, 2021).